Y_RNA (Y RNA )
Gene: Miscellaneous RNA gene on chromosome 5 (10,292,041 to 10,292,148, reverse strand). Ensembl gene ENSG00000252341.
Homologues: Orthologues: chimpanzee Y_RNA (99% identical). Paralogues in human: Y_RNA (71% identical), RNY1 (70% identical), Y_RNA (70% identical), Y_RNA (69% identical), RNY1P2 (68% identical), Y_RNA (68% identical), RNY1P11 (67% identical), Y_RNA (67% identical), RNY1P9 (66% identical), Y_RNA (66% identical), Y_RNA (65% identical), RNY1P10 (64% identical), and 85 more.